FOXA1 (forkhead box A1)
Diseases named in the same sentence as FOXA1 in open-access papers (continued):
Sharing a sentence is not in itself a finding about the gene and the disease.
maturity-onset diabetes of the young (1 paper, 2024). "Among the six detected motifs, four were highly similar to the known consensus motifs HNF1B (P = 10−38), NEUROG2 (P = 10−32), FOXA1 (P = 10−23), and RFXDC2 (P = 10−15), among which HNF1B is known to be responsible for maturity-onset diabetes of the young (MODY) type 5." (PMID 38876803, 2024).
multiple sclerosis (1 paper, 2018). A progressive autoimmune disorder affecting the central nervous system resulting in demyelination. "A previous study has shown that Foxa1 is expressed in some T-cells and that Foxa1+CD4+ T-cells represent a distinct subset of Treg which play an immunosuppressive role in the central nervous system in a mouse model of multiple sclerosis." (PMID 30061015, 2018).
necrotizing enterocolitis (1 paper, 2021). Necrotizing enterocolitis (NEC) is a devastating disease that affects mostly the intestine of premature infants. "Recently, dysregulation of intestinal FOXA1 also has been linked to necrotizing enterocolitis in infants." (PMID 33406262, 2021).
neuroblastoma (1 paper, 2024). Neuroblastoma (NB) is the most common solid, extracranial childhood tumor. "This includes FOXA1, IRF4, PAX8, and SOX10 which are respectively highly selectively essential in neuroblastoma, lymphoma, ovarian cancer, and glioma compared to all other cancer types." (PMID 39536500, 2024).
nonalcoholic fatty liver (1 paper, 2012). "We also found that human and rat nonalcoholic fatty liver (NAFL) has a reduced Foxa1 expression, which could promote the incorporation of excessive circulating lipids into hepatocytes." (PMID 22238690, 2012).
ovarian tumour (1 paper, 2024). "The pioneer transcription factor FOXA1 has been shown to be involved in ovarian tumour progression." (PMID 38612869, 2024).
Pan (1 paper, 2024). "TCGA’s Pan Cancer Atlas data indicated that several cancers present negative correlation between FOXA1 and NR3C1 transcript levels." (PMID 38015476, 2024).
periodontitis (1 paper, 2025). An acute or chronic inflammatory process that affects the tissues that surround and support the teeth. "Results showed that periodontal membrane tissues from patients with periodontitis exhibited a marked increase in FOXA1 levels." (PMID 39760528, 2025). "In conclusion, FOXA1 is a promising therapeutic target for periodontitis and deserves further investigation." (PMID 39760528, 2025). "In summary, FOXA1 was significantly overexpressed in periodontal membrane tissues of periodontitis patients, and silencing FOXA1 attenuated LPS-induced cellular inflammation and the inhibition of LPS on osteogenic differentiation of hPDLSCs." (PMID 39760528, 2025). "Immunofluorescence results indicated a notable increase in FOXA1 expression in periodontal membrane tissues of periodontitis patients (P < 0.05), and this result was consistent with the Western blot results." (PMID 39760528, 2025). "Western blot results revealed a notable rise in the level of FOXA1 protein in the periodontal tissues of periodontitis patients compared to those in healthy tissues (P < 0.05)." (PMID 39760528, 2025). "In patients with periodontitis, FOXA1 expression was found to be notably high in periodontal tissues." (PMID 39760528, 2025). "This research aims to elucidate the precise mechanisms through which FOXA1 impacts hPDLSCs and provide new insights into the treatment of periodontitis." (PMID 39760528, 2025). "However, further in vivo studies are needed to assess the effect of silencing FOXA1 on periodontitis, which are beyond the scope of the present study." (PMID 39760528, 2025). "We transfected sh-FOXA1 in hPDLSCs and found that silencing FOXA1 attenuated the promotional effect of LPS on inflammation and the inhibitory effect on osteogenic differentiation in hPDLSCs, confirming that FOXA1 plays an important role in periodontitis progression." (PMID 39760528, 2025). "Notably, treatment with LPS led to a dose-dependent increase in FOXA1 expression in hPDLSCs, indicating that FOXA1 may be involved in regulating periodontitis progression." (PMID 39760528, 2025).
relapsing-remitting multiple sclerosis (1 paper, 2015). The most common clinical variant of multiple sclerosis, characterized by recurrent acute exacerbations of neurologic dysfunction followed by partial or complete recovery. "Discovery of a novel lineage of regulatory T (Treg) cells, which are CD4+FoxA1+, as major regulators of responsiveness to IFN-β therapy in patients with relapsing-remitting multiple sclerosis (RRMS), is important for further optimization of this first in class disease-modifying therapy (DMT)." (PMID 25896927, 2015).
renal fibrosis (1 paper, 2025). A final common manifestation of a wide variety of chronic kidney diseases characterized by glomerulosclerosis and tubulointerstitial fibrosis. "This study explored the role of Hepatocyte Nuclear Factor 3 alpha (HNF3α/FOXA1) in renal fibrosis and CKD after IRI." (PMID 40091743, 2025).
salivary duct carcinoma (1 paper, 2022). An aggressive, high grade adenocarcinoma that arises from the salivary glands. "Data available in immunohistochemical studies suggested that the expression of FOXA1 in OC and salivary duct carcinoma tissue is significantly higher than that in normal tissue, and it may be a potential biomarker for cancer detection." (PMID 35273656, 2022).
small cell carcinoma of the prostate (1 paper, 2026). "Notably, in small cell carcinoma of the prostate, which typically loses expression of traditional prostate markers, FOXA1 expression was detected in 8 of 10 (80%) primary cases and 12 of 21 (57%) metastatic cases in our cohort." (PMID 42098986, 2026).
small cell lung carcinoma (1 paper, 2025). Small cell lung cancer (SCLC) is a highly aggressive malignant neoplasm, accounting for 10-15% of lung cancer cases, characterized byrapid growth, and early metastasis.
stomach adenocarcinoma (1 paper, 2021). "Among the main TFs-HRi identified, we highlight four TFs (SETD3, HOX3B, FOXA1, and SOX4) for being widely reported in association with stomach adenocarcinoma." (PMID 34416858, 2021).
thyroid (1 paper, 2021). "Novel neuroendocrine and C cell markers, such as INSM-1, ISL1, secretagonin, and FOXA1, are upcoming in thyroid oncopathology practice and under investigation." (PMID 35008368, 2021).
thyroid tumor (1 paper, 2019). A benign or malignant neoplasm affecting the thyroid gland. "This study investigated the potential role of FOXA1 expression in thyroid tumors." (PMID 32372175, 2019).
urothelial cell carcinomas (1 paper, 2012). "Furthermore, 81% of cases of SCC of the bladder were negative for FOXA1 staining compared to only 40% of urothelial cell carcinomas." (PMID 22590586, 2012).
urothelial dysplasia (1 paper, 2012). A morphologic finding indicating the presence of dysplastic changes in the transitional cell epithelium of the urinary tract. "Perhaps initial molecular “hits” resulting in the inactivation of one allele of FOXA1 occur in urothelial dysplasia/CIS, with subsequent loss of both alleles or down-regulation of the second allele occurring in more advanced MIBC." (PMID 22590586, 2012).
urothelial hyperplasia (1 paper, 2019). Hyperplasia of the transitional epithelium of the urinary tract. "Our results indicate that maintenance of urothelial hyperplasia in Upk2-HRAS* mice depends on continuous expression of Foxa1 and activated HRAS, and that mutated receptor tyrosine kinases, FOXA1 and/or other downstream effectors may mediate oncogene addiction in urothelial hyperplasia." (PMID 30670749, 2019). "We utilized the requirement of Forkhead box A1 (Foxa1) for transcriptional activation of the Upk2-promoter to temporally control the expression of Upk2-HRAS* oncogene, an inducer of urothelial hyperplasia in transgenic mice." (PMID 30670749, 2019). "Weaknesses of this study include our inability to measure the impact of Foxa1 KO on urothelial proliferation in real time, and the fact that we did not use an inducible system to reversibly control Upk2-HRAS* expression after the development of urothelial hyperplasia." (PMID 30670749, 2019).
viral infections (1 paper, 2016). "The TGFβ signaling module consists, besides the TGFβ–pathway, of related pathways regulating SMAD2/3 signaling, HIF-1 alpha transcription, coregulation of androgen receptor activity, FOXA1 transcription and some pathways related to viral infections." (PMID 26701206, 2016).
tumor (374 papers, 2007 to 2026). "Together, these findings demonstrate a tumor-suppressive role for FOXA1 as an enforcer of luminal identity, such that its loss drives basal/squamous de-differentiation, inflammatory response, and immunosuppression." (PMID 41904157, 2026). "Recently, a distinct chromatin state in ILC was identified that results in a unique FOXA1-ER axis in ILC that promotes transcription of genes associated with tumor progression and poor outcomes." (PMID 40597443, 2025). "For example, phosphorylation of the FOXA1 S331 site has been implicated in the regulation of oxidative phosphorylation and cell proliferation in PCa cells, further highlighting its role in tumor growth and metabolic adaptation." (PMID 41395253, 2025). "Mutations in DNA-binding domain of FOXA1 abrogate its tumor-suppressive function driven by heterochromatin targeting and condensate formation." (PMID 40507965, 2025). "Of note, the repression of WT1 and FOXA1, elicited by the signature, caused a downregulation of the Androgen Receptor (AR) expression, an impairment of tumor-spheroid formation and reversed cancer cell stemness." (PMID 40399259, 2025). "FOXA1 acts as a tumor suppressor, and its loss promotes NPC progression and cisplatin resistance, partially through BMI1-mediated mechanisms." (PMID 40623983, 2025). "The multifaceted role of FOXA1 in regulating gene expression highlights the distinction between oncogenic driver mutations and tumor suppressor loss-of-function mutations." (PMID 38528115, 2024). "FOXA1 plays a crucial role in normal prostate development and differentiation, and its mutation has been considered as a potential driver in tumor malignancy." (PMID 37958805, 2023). "For example, expression of FOXA1 (forkhead box A1) is highly associated with tumor purity in the Her2, luminal A and luminal B subtypes in the FPKM.UQ normalized data." (PMID 36109686, 2023). "These four 5′-tRFs tumor subtypes also showed significantly different frequencies of recurrent mutations in driver genes such as FOXA1 and KMT2D, with tF-2 having the highest frequency." (PMID 36661724, 2023). "Low FOXA1 expression has been linked to earlier tumor staging, while FOXA1 deletion has been associated with high histological grade." (PMID 36681801, 2023). "Analyzing data from loss-of-function screens, we identified a subset of NSCLC tumor lines where proliferation is FOXA1 dependent." (PMID 37691854, 2023). "Hereby, Foxa1 can act as a tumor-suppressor gene in the prostatic epithelium, even though the majority of genetic alterations in FOXA1 are found as gain of function mutations." (PMID 36139541, 2022). "Three months later, at a surveillance follow-up, UroAmplitude again detected the TERT/FOXA1 mutations, indicating tumor recurrence that was confirmed by cystoscopy." (PMID 36233691, 2022). "FOXA1 expression associates with the luminal tumor subtypes, as defined by ER and/or PGR positivity and HER2 negativity." (PMID 36171192, 2022). "In NEPC, a study of 29 tumour tissues identified single nucleotide variants (SNVs) mapped to FOXA1 in ~25% of the tumours." (PMID 32946061, 2021). "With the constant cellular tumour cellular turnover releasing cell-free DNA, liquid biopsy for FOXA1 mutations permits longitudinal tracking for residual disease and early detection for recurrence." (PMID 32946061, 2021). "Increased FOXA1 expression can also suppress the tumor immune response, which is associated with worse patient outcomes." (PMID 34680352, 2021). "Despite this loss, high-grade tumours exhibit an enrichment for FOXA1, HOXB13 and CDX2 transcription factor binding sites, indicating a shared trans-regulatory programme." (PMID 34911933, 2021).
tumor (continued). "In univariable Cox regression analysis, positive nodal status, tumor stage, and expression of FOXA1 and KRT20 were associated with worse outcome." (PMID 32252315, 2020). "Of note, FOXA1 expression has been reported to be associated with tumor progression and poor prognosis in PCa, and interestingly, FOXA1 physically interacts with AR." (PMID 31817000, 2019). "By multivariate survival analysis, FOXA1 index ≥1% was associated with longer disease-free interval and overall survival independently of the pathologic tumor size and distant metastasis." (PMID 31888566, 2019). "As further validation, we obtained diagnostic tumor tissue from two patients (PC-225 and PC-235) whose cfDNA showed FOXA1 3′-UTR mutations." (PMID 30272002, 2018). "Foxa1/2 deletion severely impairs tumor initiation and causes a proximal shift in cellular identity, yielding tumors expressing markers of the squamocolumnar junction of the gastrointestinal tract." (PMID 30475207, 2018). "This is in sharp contrast to the differentiation state of tumor cells in which FoxA1/2 loss was engineered at the time of tumor initiation, which led to an SCJ-like phenotype." (PMID 30475207, 2018). "Both transcription factors, as well as the HNF4α target PK-L, were undetectable in FoxA1/2-deficient neoplasia." (PMID 30475207, 2018). "In univariate analysis, OS was significantly associated with age (p = 0.007), tumour size (p < 0.001), nodal involvement (p < 0.001), adjuvant chemotherapy (p < 0.001), AR status (p = 0.046), AR/FOXA1 co-expression (p = 0.024) and TILs density (p = 0.023)." (PMID 29880907, 2018). "The Kaplan-Meier Plotter analysis independently validated patients with both low AR/FOXA1 tumor were significantly associated with worse relapse-free survival in ER-positive cancers." (PMID 29137314, 2017). "In another example, the risk allele (A) of rs6721996 increased the susceptibility of IGFBP5 transcription to aberrant FOXA1 expression in tumor." (PMID 26001967, 2015). "Recently, recurrent mutations in FOXA1 were observed on residues in the forkhead domain that resides near the DNA-binding surface and the mutated FOXA1 was reported to increase tumor growth." (PMID 23896594, 2013). "Logistic regression analysis demonstrated that loss of FOXA1 expression was significantly associated with increasing tumor stage (p<0.001)." (PMID 22590586, 2012). "Logistic regression analysis showed decreased FOXA1 expression is associated with increasing tumor stage (p<0.001), and loss of FOXA1 is associated with high histologic grade (p<0.001)." (PMID 22590586, 2012). "While the majority of SCC is diagnosed at a relatively advanced tumor stage, the association between SCC and FOXA1 loss remained significant (p = 0.0043) even after adjusting for tumor stage." (PMID 22590586, 2012). "As loss of FOXA1 expression was associated with increased tumor stage, we additionally performed in vitro invasion assays to determine the impact of altered FOXA1 expression in RT4 and T24 cells invasion." (PMID 22590586, 2012). "After adjusting for tumor stage, our results show a trend towards a significant association between loss of FOXA1 expression and female sex (p = 0.096)." (PMID 22590586, 2012). "While the estrogen and FOXA1 gene sets are both significantly associated with increased survival, the two sets induce substantially different partitions on the 295 tumor samples, possibly suggesting different positive mechanisms at work." (PMID 20731868, 2010). "Here, we show that prostate-specific deletion of Foxa1 in Pten-deficient mice drives tumor progression by reprogramming luminal PCa cells toward a basal/squamous-like state and promoting an immunosuppressive tumor microenvironment." (PMID 41904157, 2026).